MMP14 (matrix metallopeptidase 14)
Diseases named in the same sentence as MMP14 in open-access papers (continued):
Sharing a sentence is not in itself a finding about the gene and the disease.
tumor (continued). "Prospective evaluation by deploying MMP-14 functional assays preoperatively may inform the surgeon of the likelihood of successful tumor removal, thereby providing prognostic information to aid in patient counseling." (PMID 32848608, 2020). "The amount of MMP-14 increases with increasing grade of tumor." (PMID 32049862, 2020). "Collagen VI, DCN, and MMP14 are also functional players in the tumor microenvironment." (PMID 33317052, 2020). "In line with this, analysis of previously published gene-expression data revealed a statistically significantly higher expression of Mmp14 in HSC-derived tumor-infiltrating macrophages vs HSC-derived normal brain-engrafting microglia-like cells (available online)." (PMID 31501884, 2020). "MMP14 mediates tumor progression through vascular and immune-modulatory effects." (PMID 33050580, 2020). "By contrast, the proteolytic activity of MMP-14 was significantly different between GTR vs. STR groups, and the tumor-secreted and plasma levels of MMP-14 was found to be independent predictors of less than total tumor removal in multivariate regression analysis." (PMID 32848608, 2020). "In addition, we detected a positive correlation between expression of MGLL and MMP14 in the 76 tumor tissue samples (P = 0.036)." (PMID 33363004, 2020). "We found that MMP14 expression was significantly correlated with race, with White patients showing the highest MMP14 expression (P < 0.05), but was not significantly correlated to other clinical characteristics, such as tumor stage, gender, BMI, and age." (PMID 32974187, 2020). "MMP-14 has been showed to be activated by TGFβ1, and then plays a complex role in tumor formation, angiogenesis and invasion through destruction and reconstruction of the basement membrane 67.TGFβ1 signaling promotes migration, progression and growth of the late carcinomas." (PMID 31956360, 2020). "Similarly, miR-22 inhibits EMT via targeting EMT inducer SNAIL and ECM-remodeling MMP14, leading to the suppressed tumor growth, dissemination, and metastasis." (PMID 33321819, 2020). "The fraction of cells that produced MT-MMPs showed differences with regard to the particular MMPs and the location (infiltration zone vs. solid part of the tumor): 51% vs. 54% were positive for MMP14, 65% vs. 74% produced MMP16, and 62% vs. 86% expressed MMP17." (PMID 32872536, 2020). "Using subcutaneous models, MMP14 overexpression in cancer cells seems to reduce the cytotoxic effect of gemcitabine, whereas MMP14 inhibition in pancreatic stellate cells limits tumor growth." (PMID 32325664, 2020). "MMP14 is also highly expressed in solid cancers and mediates tumor invasion." (PMID 33317052, 2020). "The MMP-14 specific activity was higher with increasing histopathological grade of the tumor." (PMID 32049862, 2020). "Furthermore, MMP-14 assists metastasis by degrading ECM compounds during tumor invasion; however, possibly more importantly, MMP-14 enables cell survival after detachment that increases success of metastasis significantly." (PMID 32414178, 2020). "The anti-MMP14 inhibitory antibody can inhibit tumor growth, reduce tissue hypoxia, increase macrophage number, and shift cell phenotype towards the more anti-tumor M1-like phenotype due to reduced active TGFβ and SMAD2/3 signaling, hence synergistically enhancing RT effects." (PMID 33050580, 2020). "Therefore, miR-484 regulated cell adhesion and tumor growth through both directly targeting MMP14 and HNF1A." (PMID 31810492, 2019). "Thus, miR-484, who is downregulated by DNMT1-mediated hypermethylation in its promoter, functions as a tumor suppressor by inhibiting MMP14 and HNF1A expression in CC." (PMID 31810492, 2019). "Matrix metalloproteinase-14 (MMP14) is a transmembrane protein enhancing tumor growth and invasion." (PMID 30641946, 2019).
tumor (continued). "Stem cells in the tumor population expressed twice as much MMP-14 mRNA as bulk tumor cells." (PMID 30034628, 2018). "In the absence of strong cancer cell-cell interactions, constitutively high MMP14 activity can facilitate single cell invasion, thereby compromising the adhesive and expansive growth potential essential for efficient tissue colonization of the tumor cells." (PMID 29712618, 2018). "CD147 and MMPs, especially MMP-2 and MMP-14, are frequently involved in tumor cell metastasis." (PMID 28881637, 2017). "Using these three technologies, we could confirm RNA abundance as well as protein abundance of MMP14, revealing an approximate twofold higher average expression level in ccRCC tumor specimens compared to normal samples." (PMID 28596300, 2017). "Indeed, staining of immune cell markers in 4T1 tumor tissue sections revealed that MMP-14 blockade led to a skewing of the TME." (PMID 28938563, 2017). "In addition, CD44 has been shown to directly interact with MMP-14 (MT1-MMP) to promote tumor cell invasion." (PMID 29348826, 2017). "In contrast to tubular and alveolar structures, these morphological variants demonstrate high expression of the VASN gene which is known to be enriched in the trailblazer cells and begin to express the MMP14 gene (MT1-MMP) that is essential for tumor cell invasion." (PMID 28977854, 2017). "In the MMTV-PyMT mouse model Mmp14 is required for efficient tumor dissemination." (PMID 27542270, 2016). "Immunohistochemistry was performed in order to examine IL-6 and MMP14 expression in human tumor samples and to determine whether the proteins were associated with clinical parameters such as pathological grade and patient survival." (PMID 27613828, 2016). "MMP-14 (membrane-type 1 matrix metalloproteinase) is involved in aggrecan degradation and cadherin cleavage and has been shown to be involved in inhibition of tumor angiogenesis." (PMID 27478294, 2016). "In addition to MMP2 and MMP9, we investigated the expression of MMP3, MMP11, MMP13 and MMP14 in tumour cells." (PMID 26284589, 2015). "We found that the expression level of Hes1 or MMP14 mRNA was unrelated to the tumor stage." (PMID 26650241, 2015). "A previous study showed that selective inhibition of MMP-14 blocks tumor angiogenesis." (PMID 25233229, 2014). "However, MMP14 (MT1-MMP) expression in tumor cells was highly elevated in Apcmin/+/Stat3IEC-KO mice but undetectable in Apcmin/+ mice." (PMID 24995503, 2014). "These abnormal expression patterns may have an important role in tumor development and metastasis, and suggest that semaphorin-3A may be a suppressor gene and MMP-14 an oncogene." (PMID 24765144, 2014). "However, MMP2, MMP9 and MMP14 are the three major MMPs reported to be involved in tumor angiogenesis." (PMID 25071013, 2014). "Since MMP14 is particularly efficient in hydrolyzing basement membranes, it may be involved in tumor invasion in Apcmin/+/Stat3IEC-KO mice." (PMID 24995503, 2014). "Despite a clear correlation between MMP14 expression and tumor grade, it remains unclear whether expression of MMP14 has any prognostic significance." (PMID 24156018, 2013). "Thus, high CD3, CD20 or CD68 counts were significantly associated with MMP-9 expression, at the invasive front; whereas high CD68 count was significantly associated with MMP-14 and TIMP2 in this same tumor location." (PMID 23300781, 2012). "MMP-14 has been correlated with tumor invasion, metastases, and poor patient prognosis." (PMID 22567163, 2012). "On the basis of GEO data, MMP14 was found up-regulated in the tumour samples, but it was not discussed in the papers associated to the datasets." (PMID 19753302, 2009). "Using immunohistochemistry we found MMP-14 protein to be localized in the cytoplasm of tumor cells with only slight additional staining of the surrounding stroma cells, whereas no staining in normal breast tissue could be detected." (PMID 19531263, 2009).
tumor (continued). "MMP14 is a member of the matrix metalloproteinases (MMP) protein family, involved in the breakdown of extra-cellular matrix that has been associated with many different tumours." (PMID 19753302, 2009). "Additionally, Lumican may protect collagen from MMP‐14 proteolysis, influencing cell‐matrix interaction in tumour progression." (PMID 41546170, 2026). "Beyond these mechanistic insights, determining whether ACC’s dependency on MMP-14 represents a general feature of aggressive cancers or a tumor type-specific vulnerability will be essential for predicting which patients are most likely to benefit from MMP-14-targeted therapies." (PMID 41542511, 2026). "However, in supraglottic carcinoma, MMP-14 appears more influential in tumor progression." (PMID 41281748, 2025). "However, recent studies have suggested that MMP-14 may also contribute to normalizing tumor vasculature, improving drug delivery and reducing tumor aggressiveness induced by hypoxia." (PMID 39199626, 2024). "Therefore, the UCA1/miR-485-5p/MMP14 axis may provide a potential strategy for targeting tumor metastasis-related therapies." (PMID 38725621, 2024). "Additionally, MMP-14 may enhance anti-tumor immunity by modulating immune cell activity within the tumor microenvironment." (PMID 39199626, 2024). "In addition, MMP14 derived from tumour cells activates mesenchymal cells and CAFs in the TME." (PMID 36765296, 2023). "In combination with previous studies, our present results indicate a positive correlation between MMP14 expression at the TSI and clinicopathological features of metastasis, which may be linked to EMT, and that tumour immunity might affect the metastatic process." (PMID 36765296, 2023). "Interestingly, the expression of ECT2, FGD6, MMP14, and SLC2A1 were statistically different in the patients with different tumor stage, which implied that ECT2, FGD6, MMP14, and SLC2A1 might be associated with the development of PC." (PMID 37604837, 2023). "Therefore, CEMIP may have a positive correlation with MMP2, MMP7, MMP13, and MMP14 and regulate tumor cell EMT through MMPs to promote tumor cell migration." (PMID 37662915, 2023). "Thus, we isolated tumor cells from vehicle-treated, γδ T cell-treated or γδ T cell MMP14-treated mice after tumor resection and analyzed the degranulation capacity of γδ T cells in response to these xenograft-derived tumor cells (indicated as “xeno” in the figures)." (PMID 37139603, 2023). "MMP14 is over expressed in cancer tissues and may be involved in tumor progression of GC." (PMID 37370118, 2023). "Importantly, its in vivo anti-tumor effect was associated with the disruption of immunosuppressive TME, including limiting tumor neoangiogenesis and hypoxia, suggesting that MMP-14 inhibitory antibody suppresses tumor progression and metastasis through its effect on TME in TNBC." (PMID 36741729, 2022). "Finally, MMPs, such as MMP-14, also participate in tumor immune monitoring." (PMID 36776395, 2022). "Furthermore, MMP14 staining revealed mainly positive cells in the tumor border, which could reflect the invasive front in both models." (PMID 36230481, 2022). "Interestingly, in another study, the increased expression of MMP-14 was associated with early stage OvCa, low CA125 levels, and inversely correlated with tumor progression, suggesting that MMP-14 may have some protective prognostic value." (PMID 36077371, 2022). "The evaluation of ENG and MMP14 expression in a larger cohort of patient samples showed that high ENG levels were significantly associated with worse prognosis, suggesting that this protein could contribute tumor aggressiveness." (PMID 35955799, 2022). "Whether MMP14 can be used as a biomarker for tumor prognosis needs further study." (PMID 34604053, 2021). "Examination of MMP-14 levels in the serum of patients with post-radiated tumors or after treatment of primary VS cultures with ionizing radiation may provide insight into radiation-mediated changes in tumor biology." (PMID 32848608, 2020).
tumor (continued). "Thus, we hypothesize that the inflammatory response and tumor immunity regulated by MMP14 and M0 macrophage density may have a connection with tumor prognosis and progression in DLBCL patients." (PMID 32974187, 2020). "Once activated, tumor associated myeloid cells contribute to tumor proliferation by secreting oncogenic factors such as EGFR, extracellular matrix (ECM) remodeling by releasing proteases such as MMP2 and MMP14 and induction of angiogenesis by secretion of proangiogenic factors." (PMID 32038644, 2019). "In addition to reducing dissemination of tumor stem cells, as would be expected from inhibition of MMP-14's ability to degrade components of the extracellular matrix, IgG 3A2 also inhibited the ability of individual stem cells to proliferate and produce colonies." (PMID 30034628, 2018). "In addition, ΔCRE cells showed a significant alteration in the levels of matrix metalloproteinase MMP14 that has an important role in tumor invasion by regulating the levels of collagens, extracellular matrix (ECM) proteins and factors involved in epithelial–mesenchymal transition." (PMID 30467308, 2018). "More germane to the present focus of this study on tumor invasion, however, the BioID data also surprisingly demonstrate that CAIX associates with cell surface pro-invasive and matrix modeling proteins such as β1 integrins, integrin associated proteins (CD98hc) and MMP14." (PMID 28692057, 2017). "The local regulation of endoglin shedding, mediated by regulation of endothelial MMP-14 expression, could result in remarkable changes in soluble endoglin concentration in the tumour microenviroment, with consequent effects on the angiogenic potential of tumour-associated endothelial cells." (PMID 26296972, 2015). "Taken together, cld7 promotes tumor cell motility, which is accompanied by phosphorylated cld7 associating with CD49c and CD104, and supports invasiveness, which could be provoked by the colocalization of cld7 with MMP14 in GEM." (PMID 25514462, 2015). "In addition, the expression of semaphorin-3A correlated with the maximum diameter of the tumor, while MMP-14 expression revealed no such association." (PMID 24765144, 2014). "Therefore, we show that the inhibition of MMP14 sensitizes tumor cells to TMZ and XRT and could be used as a future strategy for antiglioma therapy." (PMID 24156018, 2013). "In an investigation of gene expression during tumor progression in the breast, it was found that extensive changes in gene expression occur in tumor-associated stroma, including increased expression of MMP2, MMP11, and MMP14 during the transition from a preinvasive to invasive phenotype." (PMID 21647291, 2011). "Mechanistically, ZFAS1 functions as a competitive endogenous RNA (ceRNA) that sequesters tumor-suppressive miRNAs including miR-150 and miR-193a-3p, thereby de-repressing downstream oncogenic targets such as ZEB1/MMP14 and RALY/HGF/c-Met." (PMID 41450817, 2026). "Genetic silencing or pharmacologic inhibition of MMP-14 significantly reduced viability in both NCI-H295R cells and patient-derived tumor organoids (PTOs)." (PMID 41542511, 2026). "Among them, we focused on matrix metalloproteinase 14 (MMP14), an important protein involved in the EMT process in tumor cells." (PMID 40178046, 2025). "MMP-14 or MT1-MMP is also a promising target due to its role in local ECM degradation and in activating other MMPs, including MMP-2, on the tumor cell surface." (PMID 40265458, 2025). "In vivo MRI assessment of tumor-bearing mice in the present studies enabled volume-wise spatial analyses between the GBM orthotopic xenografts and the radiolabeled MMP-14 targeted peptide probes." (PMID 40093889, 2025). "Among the matrix metalloproteinases, membrane-type matrix metalloproteinase 1 (MT1-MMP/MMP14) is the first identified membrane-type MMP and acts as an essential proteolytic enzyme that enables tumor infiltration and metastatic progression." (PMID 40196128, 2025).
tumor (continued). "MMP-14, a membrane-type MMP, is also central to tumor invasion, as it activates other MMPs, such as MMP-2, on the cell surface, further enhancing pericellular matrix degradation and enabling cells’ infiltration in GBM." (PMID 40265458, 2025). "As a matrix metalloproteinase (MMP), MMP14 is involved in the degradation of various ECM components and processing and shedding membrane-bound proteins, which makes it capable of tumor-related functions." (PMID 40407957, 2025). "For example, we detected with our untargeted newsECM proteomics analysis the augmented synthesis of MMP-14 in dECM-tumors, which has been reported as the driving force behind ECM destruction during tumor cell invasion." (PMID 40166338, 2025). "In mammary epithelial cells, MMP14 directly interacts with integrin β1 to regulate MAPK signaling, thereby facilitating tumor cell invasiveness." (PMID 40766297, 2025). "The primary objective of this study was to elucidate the clinical significance and predictive value of MMP14 in CRC, including its comprehensive involvement in tumor-infiltrating immune cells." (PMID 40352589, 2025). "MMP-14, also known as MT1-MMP, is a promising drug target in various malignancies due to its direct involvement in tumor growth, migration, and collagen degradation." (PMID 40869275, 2025). "Some studies using high-resolution multimodal microscopy confirm that MMP-14-driven pericellular proteolysis enables single-cell and collective-cell migration, reinforcing the importance of ECM remodeling in tumor invasion." (PMID 41281748, 2025). "Isoform structure analysis using GEPIA2 revealed functional diversity in MMP7, MMP11 and MMP14, highlighting their roles in ECM degradation and tumor progression." (PMID 40604111, 2025). "The downregulation of hsa-miR-195-5p results in the overexpression of MMP14 and HDGF, which act as tumor promoters and are both targeted by hsa-miR-195-5p." (PMID 38342922, 2024). "MMP14 inhibition by NSC405020 (MMP14i, 2 mg/kg/day) led to a more robust tumor regression and decreased tumor vascularization, resulting in approximately 90% avascularity of tumor tissues but not adjacent regions." (PMID 38329810, 2024). "However, MMP-14 has complex roles that may vary based on the tumor context." (PMID 39199626, 2024). "Consistent with previous reports, MMP14 and OPN expression was also detected on tumor macrophages and EpCAM+ tumor cells, however, at 2- to 3-fold lower levels compared with TANs, indicating TANs as a major source of MMP14 and OPN in the CRC tumor niche." (PMID 38329810, 2024). "MMP-14, or MT1-MMP, is known to degrade extracellular matrix components and activate other MMPs, facilitating tumor invasion." (PMID 39199626, 2024). "In vitro, it has been shown that furin had the potential to convert SCC-related matrix metallopeptidase 14 (MMP14) zymogen into its active form, required for collagen degradation by the tumor cells." (PMID 38489333, 2024). "In human ovarian cancer, antibody-secreting cells generate tumor-reactive IgG antibodies targeting MMP14, demonstrating in vitro ADCP induction and tumor growth inhibition." (PMID 39519376, 2024). "MMP-14, in turn, degrades the extracellular matrix (ECM) and facilitates tumor invasion and angiogenesis." (PMID 39199626, 2024). "This analysis prompted a focus on specific MMPs more distinctly expressed in CC2, such as MMP2, MMP9, MMP11, MMP14, and MMP25, suggesting their potential role in tumor invasion and their clinical relevance as potential therapeutic targets." (PMID 38893149, 2024). "The only MMPs with lowered expression in neoplasm tissue were MMP2 and MMP14 independently of the cancer grade." (PMID 38397798, 2024). "The macrophages in the invasive zone exhibited an M2-like phenotype with increased expression of CD163, MRC1, and SAAs receptor TLR2, whereas macrophages in the tumor tissue exhibited features of ECM remodeling and increased expression of MMP9 and MMP14." (PMID 37337030, 2023).